BCL2 (BCL2 apoptosis regulator)
Diseases named in the same sentence as BCL2 in open-access papers (continued):
Sharing a sentence is not in itself a finding about the gene and the disease.
chronic lymphocytic leukemia (continued). "Venetoclax (Bcl-2-selective inhibitor) is used to treat small lymphocytic lymphoma (SLL), which mainly promotes tumor cell apoptosis by inhibiting Bcl-2 and, ultimately, activating caspase-3." (PMID 36612023, 2022). "The first clinically approved BH3-mimetic, ABT199 (venetoclax), specifically targets BCL-2 and is currently used in chronic lymphocytic leukemia (CLL) and AML, which are often dependent upon BCL-2 for cancer cell survival." (PMID 35349392, 2022). "It has been reported that the transcript levels of STAT3-regulated anti-apoptotic genes Bcl-2 and MCL-1 or proapoptotic gene such as caspase-3 were both upregulated in Chronic lymphocytic leukemia (CLL) cells from patients and myeloid cells." (PMID 36615735, 2022). "ABT-199 (Venetoclax) is the first Bcl-2 inhibitor approved by FDA for the treatment of patients with chronic lymphocytic leukemia, small lymphocytic lymphoma (SLL) and acute myeloid leukemia (AML)." (PMID 36386146, 2022). "One such promising therapy, which has recently been approved as a standard treatment option for CLL and small lymphocytic lymphoma, is venetoclax (ABT-199), which is a Bcl-2-specific protein inhibitor." (PMID 36099249, 2022). "Nowadays, many patients with chronic lymphocytic leukemia (CLL) are treated with so-called novel agents, including BTK inhibitors, Bcl-2 inhibitors and PI3K inhibitors." (PMID 33809580, 2021). "Only one BCL2 inhibitor, ABT199 (Venetoclax), has been approved by the Food and Drug Administration (FDA) to treat Chronic Lymphocytic Leukemia or Small Lymphocytic Lymphoma and Acute Myeloid Leukemia6,11,20." (PMID 33976278, 2021). "Venetoclax, a selective BCL2-inhibitor, was initially approved by the US Food and Drug Administration (FDA) for chronic lymphocytic leukemia." (PMID 34548471, 2021). "In some hematological malignancies, such as chronic lymphocytic leukemia, cells mostly express the BH3-only proteins BIM and PUMA, which are constitutively bound to BCL-2." (PMID 33806619, 2021). "For example, in patients with chronic lymphocytic leukemia (CLL), low MCL1 expression and high BIM:MCL-1 or BIM:BCL-2 ratios correlate with increased response to navitoclax (BCL-2/BCL-XL/BCL-W inhibitor)." (PMID 35008216, 2021). "Venetoclax is effective in the clinic as a monotherapy against chronic lymphocytic leukemia (CLL), which expresses BCL-2 at high levels, as well as in AML and other hematologic malignancies." (PMID 34065859, 2021). "Of notable success is the Bcl-2-specific inhibitor Venetoclax (ABT-199), which has been FDA-approved for the treatment of chronic lymphocytic leukemia (CLL), small lymphocytic lymphoma (SLL), and acute myeloid leukemia (AML)." (PMID 34943974, 2021). "On the other hand, in chronic lymphocytic leukemia (CLL), large B-lymphoma cells, and multiple myeloma, the antiapoptotic protein Bcl-2 binds the InsP3R, suppressing its activity to prevent cytosolic Ca2+ increase-mediated apoptosis." (PMID 33440859, 2021). "Expression levels of miR-15a and miR-16-1 correlated negatively to Bcl-2 expression in chronic lymphocytic leukemia (CLL), which was characterized by malignant B cells with overexpression of Bcl-2." (PMID 32182776, 2020). "Currently, venetoclax is the only approved drug by the FDA for the treatment of chronic lymphocytic leukemia (CLL), and it is a selective BCL-2 protein inhibitor." (PMID 32328476, 2020). "To study the role of BCL2 in HSC activation and fibrosis, we used Venetoclax, a selective inhibitor approved by the Food and Drug Administration (FDA) for chronic lymphocytic leukemia patients with chromosome 17 p deletion." (PMID 32650615, 2020). "ABT-263 (navitoclax) was another potent inhibitor of BCL-2, BCL-XL and BCL-w, showing activity in chronic lymphocytic leukemia (CLL), but its clinical development was halted due to dose-limiting severe thrombocytopenia resulting from BCL-XL inhibition." (PMID 32183335, 2020).
chronic lymphocytic leukemia (continued). "Venetoclax is an orally bioavailable, B-cell lymphoma-2 (BCL-2) selective inhibitor, used for the treatment of various types of blood cancers, such as chronic lymphocytic leukemia (CLL) and small lymphocytic lymphoma (SLL)." (PMID 32645956, 2020). "Venetoclax, the first-in-class Bcl2 inhibitor, was approved by the US FDA to treat chronic lymphocytic leukemia in 2016." (PMID 33097020, 2020). "Clinical trials that utilize BCL‐2 inhibitors are becoming more and more prevalent and could potentially show exciting results as an efficient treatment for many different forms of blood cancer, such as chronic lymphocytic leukemia, acute myeloid leukemia and Non‐Hodgkin's lymphoma." (PMID 38831555, 2020). "In this regard, in 2016, the specific BCL-2 inhibitor venetoclax (ABT-199), was approved by the Food and Drug Administration (FDA) for relapsed Chronic lymphocytic leukemia (CLL) with 17p deletion." (PMID 32486249, 2020). "In this study, we studied venetoclax (Venclexta, Venclyxto, ABT-199, GDC-0199, RG7601), a potent and selective BCL-2 inhibitor, approved by the FDA in 2016 for the treatment of patients with chronic lymphocytic leukemia (CLL) with 17p deletion." (PMID 32085398, 2020). "This was followed by the introduction of a BCL-2-specific inhibitor, ABT-199 (Venetoclax), which has received approval for treating refractory chronic lymphocytic leukemia (CLL), where BCL-2 addiction is a key feature in the pathogenesis of the disease." (PMID 30185825, 2019). "MiR-16 was first reported to be decreased in chronic lymphocytic leukemia (CLL) due to the deletion in chromosome 13q14 and inhibited apoptosis through targeting Bcl-2." (PMID 31262262, 2019). "Venetoclax, a BCL2 specific inhibitor, has been approved for the treatment of chronic lymphocytic leukemia (CLL), which originates from BCL2-dependent B cells." (PMID 31231360, 2019). "The anti-apoptotic protein Bcl-2 is upregulated in several cancers, including diffuse large B-cell lymphoma (DLBCL) and chronic lymphocytic leukemia (CLL)." (PMID 30416758, 2018). "BCL2-inhibitor venetoclax is used to treat relapsed/refractory chronic lymphocytic leukemia (CLL)." (PMID 29463802, 2018). "Chronic Lymphocytic Leukemia (CLL) cells are highly dependent on BCL-2 expression for survival." (PMID 29732004, 2018). "When used in combination with BCL-2 inhibitors, these SF3B1 inhibitors have been demonstrated to induce apoptosis in small lung cancer cells, chronic lymphocytic leukemia cells and head and neck cancer cells." (PMID 28884683, 2017). "CQ and HCQ can activate caspase-3 and modulate the Bcl-2/Bax ratio inducing apoptosis in CLL, B-cell CLL and glioblastoma cells." (PMID 29225688, 2017). "It is a major mechanism of cell death in chronic lymphocytic leukaemia (CLL), induced by drugs that target Bcl-2 and the proteasome." (PMID 29163771, 2017). "The second, venetoclax, developed by AbbVie and Genentech, binds to BCL-2 and blocks its interaction with other proteins; this gained FDA approval in 2016 for chronic lymphocytic leukaemia (CLL)." (PMID 28875019, 2017). "Venetoclax (ABT-199), a first-in-class orally bioavailable BCL-2-selective inhibitor, was recently approved by the FDA for use in patients with 17p-deleted chronic lymphocytic leukemia who have received prior therapy." (PMID 28578655, 2017). "The miR-15a/16-1 cluster at 13q14.3 is frequently deleted in B-cell chronic lymphocytic leukemia (B-CLL), and miR-15a and miR-16-1 are bona fide tumor suppressors, which act by targeting oncogene Bcl-2." (PMID 27191272, 2016).
chronic lymphocytic leukemia (continued). "For chronic lymphocytic leukemia (CLL), high BCL-2 and MCL-1 expression levels have been reported to mediate resistance to chlorambucil, fludarabine, and rituximab." (PMID 26537004, 2015). "The Bcl-2 protein is elevated in a variety of types of cancer, including those derived by malignant transformation of B-lymphocytes: chronic lymphocytic leukemia (CLL), follicular lymphoma (FL), and multiple myeloma (MM)." (PMID 26317541, 2015). "Nucleolin functions to stabilize Bcl-2 mRNA by protecting it from RNase degradation by binding to an AU-rich element (ARE) in the 3′-UTR of Bcl-2 mRNA in HL-60 and chronic lymphocytic leukemia cells." (PMID 25290311, 2014). "ABT-737 can overcome BCL2 and BCL-XL and is currently in phase 1 clinical trial in small cell lung cancer (SCLC) and chronic lymphocytic leukaemia." (PMID 24887326, 2014). "The atypical lymphocytes were immunohistochemically positive for CD20, Bcl-2, CD23, and CD5 consistent with B-cell chronic lymphocytic leukemia/small lymphocytic lymphoma (B-CLL/SLL)." (PMID 24385769, 2013). "Antisense oligonucleotides targeting Bcl-2 have also been developed and in one case have reached a phase III clinical trial in patients with chronic lymphocytic leukemia." (PMID 22683550, 2012). "Previously, we showed that inhibition of GSK-3 resulted in apoptosis induction through decreased expression of NF-κB target genes Bcl-2 and XIAP in chronic lymphocytic leukaemia (CLL) and pancreatic cancer cells." (PMID 19920820, 2009). "As one example, ABT-199 (venetoclax), which inhibits the interaction of BCL-2 with downstream pro-apoptotic proteins, represents the first small-molecule PPI inhibitor approved for the treatment of chronic lymphocytic leukemia, small lymphocytic lymphoma, and acute myeloid leukemia." (PMID 40231473, 2025). "Venetoclax, a bona fide synthetic BH3 mimetic that is a selective inhibitor of the BCL‐2 protein, is approved for use in several hematologic malignancies, including acute myeloid leukemia (AML) and chronic lymphocytic leukemia (CLL), either as a monotherapy or in drug combinations." (PMID 40370107, 2025). "An example of anti-BCL-2 precise treatment is the drug venetoclax since it blocks the mitochondrial anti-apoptotic B-cell lymphoma-2 (Bcl-2) protein, leading to programmed cell death of CLL cells or small lymphocytic lymphoma (SLL)." (PMID 40573308, 2025). "Chronic lymphocytic leukemia (CLL) treatment has undergone a significant evolution with a shift from historical chemotherapeutic regimens to targeted therapies such as Bruton tyrosine kinase (BTK) and BCL-2 inhibitors." (PMID 39796746, 2025). "The therapeutic landscape of Chronic Lymphocytic Leukemia (CLL) has dramatically changed in recent years, with a shift from chemoimmunotherapy towards many new targeted agents, such as Bruton Tyrosine Kinase inhibitors (BTKi) and anti-BCL-2." (PMID 39456577, 2024). "The second example involves the BCL-2/BCL-XL dual inhibitor navitoclax (ABT-263) and the BCL-2-specific inhibitor venetoclax (ABT-199), which are designed to treat patients with relapsed or refractory chronic lymphocytic leukemia." (PMID 38675453, 2024). "Venetoclax is a BCL-2-selective small-molecule inhibitor that is FDA-approved in combination with other agents for the treatment of adults with chronic lymphocytic leukemia, small lymphocytic lymphoma, or AML." (PMID 39199601, 2024). "These include the Bcl2-selective BH3-mimetic Venetoclax, which is currently used for the treatment of chronic lymphocytic leukemia, small lymphocytic lymphoma, or acute myeloid leukemia, or the myeloid cell leukemia-1 (Mcl-1) inhibitors S63845, AMG-176, and AZD5991." (PMID 38275765, 2024). "Venetoclax is the only FDA-approved small-molecule inhibitor against BCL2 in acute myeloid leukemia (AML), and chronic lymphatic leukemia—yet other drugs might follow both in hematologic and solid tumor malignancies." (PMID 37055532, 2023).
chronic lymphocytic leukemia (continued). "Indeed, venetoclax, the first BCL-2 inhibitor approved by the FDA, is a mild and efficient drug for treating chronic lymphocytic leukemia and acute myeloid leukemia, especially when combined with other anticancer agents." (PMID 37108344, 2023). "We decided to focus on BCL2, because it is the sole target for which an FDA/EMA-approved drug is available for the treatment of specific blood cancers (in particular, acute myeloid leukemia, chronic lymphocytic leukemia and small lymphocytic leukemia)." (PMID 37623817, 2023). "Additionally, the highly selective Bcl-2 inhibitor, Venetoclax (VIII), is now approved for treatment of chronic lymphocytic leukemia (CLL) patients with a 17p chromosomal deletion who have received at least one prior therapy." (PMID 35163939, 2022). "Indeed, Venetoclax, a selective BCL-2 inhibitor, has been the first BH3-mimetic approved for a subset of patients with Chronic Lymphocytic Leukemia or Acute Myeloid Leukemia21,53,54." (PMID 35256598, 2022). "The potent oral inhibitor of BCL2, venetoclax (VEN), used to treat adults with chronic lymphocytic leukaemia, has been approved in US for the treatment of naïve patients with acute myeloid leukemia (AML) unfit for intensive chemotherapy and recently in Europe, too." (PMID 34899303, 2021). "However, it was not until 2016 that the first of these drugs, Venetoclax which specifically targets BCL-2, was granted FDA approval for relapsed chronic lymphocytic leukaemia (CLL) patients with 17p deletion." (PMID 34581776, 2021). "Bcl2 is the target of Venetoclax26 (Drug-2), a BH3 chemical mimetic that blocks the anti-apoptotic Bcl2 protein and is clinically-approved for chronic lymphocytic leukemia (CLL) or small lymphocytic lymphoma (SLL) treatment." (PMID 34599176, 2021). "The selective BCL2 inhibitor ABT-199 (venetoclax), approved by the FDA for acute myeloid leukemia and chronic lymphocytic leukemia, demonstrated notable activity in a phase I clinical trial when combined with tamoxifen in ER+/HER2− ABC patients with BCL2 overexpression." (PMID 34771560, 2021). "Further, while being effective in cancers that depend on BCL2 for survival, such as chronic lymphocytic leukemia (CLL), resistance to ABT-199, as well as other inhibitors of BCL2, can occur through upregulation of other anti-apoptotic proteins such as BCL-XL, BFL1 (BCL2A1), or MCL1." (PMID 32824203, 2020). "ABT263, also known as Navitoclax, is an orally active anti-cancer drug, that disrupts BCL2/BCL-XL interactions and has been evaluated in several clinical trials of chronic lymphocytic leukemia, non-small cell lung cancer, ovarian cancer, and some other solid tumors." (PMID 32235588, 2020). "Furthermore, our study revealed that Venetoclax, a BCL2 inhibitor, approved by FDA for chronic lymphocytic leukemia, inhibited stellate cell proliferation and activation in vitro and impeded liver fibrosis in miR-122 knockout mice." (PMID 32650615, 2020). "Navitoclax is the first in-class oral BCL-2 (and BCL-XL) dual inhibitor that showed antileukemic activity in chronic lymphocytic leukemia (CLL), however, its further development has been limited by its target specific (BCL-XL) dose-limiting severe thrombocytopenia." (PMID 33251134, 2020). "Thus far, a specific inhibitor for BCL2 (ABT-199, Venetoclax) obtained approval for treatment of chronic lymphocytic leukemia (CLL)." (PMID 31013740, 2019). "It has been shown that bcl2, bcl-XL and mcl-1 protein levels are high in chronic lymphocytic leukemia cells, and resultantly, apoptosis does not occur chronic lymphocytic leukemia cells." (PMID 31718601, 2019). "ABT-199, a Bcl-2 selective inhibitor, does not induce thrombocytopenia and is clinically applied to treat chronic lymphocytic leukemia patients." (PMID 29520102, 2018).
chronic lymphocytic leukemia (continued). "More recently, a Bcl-2-selective BH3-mimetic inhibitor was developed, namely ABT-199/venetoclax, which is a very promising anti-cancer drug that has been approved for the treatment of chronic lymphocytic leukemia." (PMID 28516063, 2017). "Other studies showed that there was a correlation between the expression of Bcl-2 and an absence of miR-15 and miR-16, which is important in the regulation of apoptosis in chronic lymphocytic leukemia." (PMID 22159405, 2012). "For example, in multiple studies, increased levels of Bcl-2, Bcl-xL, and Mcl-1 proteins were linked to survival of multiple myeloma cells and resistance to chemotherapy, while in most cases of chronic lymphocytic leukemia (CLL), elevated Bcl-2 mRNA and protein levels are noted." (PMID 23233904, 2012). "Indeed, mice overexpressing in B cells both a TRAF2 mutant that mimics TRAF1 and Bcl-2 develop Small B-cell Lymphoma (SBL) and Chronic Lymphocytic Leukemia (CLL) with high incidence." (PMID 17593960, 2007). "Approved BTKis, given as continuous therapy for a prolonged time, and fixed-duration venetoclax (BCL-2 inhibitor) in combination with an anti-CD20 monoclonal antibody (obinutuzumab or rituximab) are the mainstay treatments for front-line and relapsed/refractory chronic lymphocytic leukemia." (PMID 40737507, 2025). "Pharmacological BH3 mimetics, such as venetoclax (a BCL-2-selective inhibitor) and navitoclax (a dual BCL-2/BCL-xL inhibitor), directly trigger MOMP and have achieved remarkable clinical efficacy in hematologic malignancies, including chronic lymphocytic leukemia and acute myeloid leukemia." (PMID 41551149, 2025). "This translocation and other alterations of the BCL2 locus architecture, such as either translocation to Ig light chain genes or chromosomal amplifications of the BCL2 locus, are also documented either in some rare FL cases, in DLBCL or in chronic lymphocytic leukemia cases." (PMID 36358756, 2022). "Venetoclax (VEN) is the first selective small molecule Bcl-2 inhibitor approved by FDA and used in adult chronic lymphocytic leukemia (CLL), small lymphocytic lymphoma (SLL) and some acute myeloid leukemia (AML)." (PMID 36477747, 2022). "The more selective BCL-2 inhibitor, ABT-199 (venetoclax), was developed subsequently and became the first BH3-mimetic approved by the United States Food and Drug Administration (FDA) for patients with chronic lymphocytic leukemia/small lymphocytic lymphoma (CLL) with chromosome 17p deletion." (PMID 34198580, 2021). "Venetoclax is a potent and selective BCL-2 inhibitor, approved by the FDA in 2016 for the treatment of patients with chronic lymphocytic leukemia (CLL)." (PMID 32085398, 2020). "The archetypal member of the Bcl-2 anti-apoptotic gatekeeper protein family is a well-studied drug target, validated in recent years by the clinical approval of Venetoclax (ABT-199) for the treatment of chronic lymphocytic leukemia, small lymphocytic lymphoma and acute myeloid leukemia." (PMID 33256166, 2020). "Thus, BCL-2 has become an attractive target for therapeutic strategy in cancer, as demonstrated by the recent approval of ABT-199 (VenclextaTM) in relapsed or refractory Chronic Lymphocytic Leukemia with 17p deletion." (PMID 29732004, 2018). "Navitoclax (ABT-263), an orally bioavailable small-molecule inhibitor of BCL-2, BCL-XL, and BCL-W, showed signs of clinical antitumor activity in chronic lymphocytic leukemia (CLL)." (PMID 28578655, 2017). "Furthermore, high expression of Bcl-2 but not Bcl-xL correlates with sensitivity to ABT-737 in chronic lymphocytic leukemia." (PMID 26447615, 2015). "Chronic lymphocytic leukemia (CLL) treatment has evolved from traditional chemotherapy to targeted therapies, such as Bruton tyrosine kinase (BTK) and BCL-2 inhibitors with significant improvements in survival rates and a transformation of CLL into a manageable, chronic condition." (PMID 39796746, 2025).